AHR (aryl hydrocarbon receptor)
Diseases named in the same sentence as AHR in open-access papers (continued):
Sharing a sentence is not in itself a finding about the gene and the disease.
colon carcinoma (continued). "As SCD1 plays vital roles in CRC and in colon cancer cells, the potential role of the AhR in control of SCD1 expression in colon tumor cells deserves more attention." (PMID 36077780, 2022). "We observed that the AhR is upregulated in tumor epithelial cells derived from colon cancer patients." (PMID 36077780, 2022). "It has been reported that AhR knockdown mediated by siRNA can increase proliferation of colon cancer cell lines." (PMID 36077780, 2022). "This confirmed that the AhR is upregulated directly in colon cancer epithelial cells, and that the observed upregulation in whole tumor tissue was not linked with stromal cells, or with other cell types infiltrating the tumor tissue." (PMID 36077780, 2022). "More attention should be paid to potential mechanistic links between overexpressed AhR and colon tumor cell metabolism." (PMID 36077780, 2022). "Several reports have indicated that AhR mRNA and/or AhR protein can be upregulated in colon tumor tissue." (PMID 36077780, 2022). "We also found reduced mRNA levels of key enzymes of the FA biosynthetic pathway in AhR KO colon cancer cells, in particular of stearoyl-CoA desaturase 1 (SCD1)." (PMID 36077780, 2022). "Taken together, this study reports for the first time, single and combinatory effects of Uro A, AOH, and DON on intestinal AhR activation and implications toward the epithelial structural integrity and metabolic capacities of colon cancer." (PMID 35811943, 2022). "We observed that the AhR levels were higher in colon cancer tissue, as compared with the adjacent healthy tissue." (PMID 36077780, 2022). "The SCD1 levels were also significantly reduced by two chemical AhR antagonists (CH-223191 and StemRegenin 1) in colon cancer cells." (PMID 36077780, 2022). "In order to further verify our observations of the impact of the AhR loss on cell proliferation and expression of FA synthesis genes in colon cancer cell lines, we next used the AhR antagonist CH-223191, in order to inhibit the AhR signaling." (PMID 36077780, 2022). "We found that, in addition to decreasing cell numbers in colon cancer cells, the AhR antagonist CH-223191 significantly impaired activation of the Akt pathway." (PMID 36077780, 2022). "Results from this trial will be important to understand the effect of AhR modulation in colon cancer progression." (PMID 33916690, 2021). "Urolithins (UroA), gut microbiota-derived metabolites of the natural polyphenol ellagic acid, have been shown to antagonize AhR and induce senescence in human colon cancer cells and prostate cancer." (PMID 33451095, 2021). "Results from an earlier colon cancer study also suggest that the original AhR-bound Src is released and activated after AhR activation." (PMID 34769098, 2021). "Recently, however, a trial using an AhR inhibitory drug (BAY2416964) was initiated for treatment of advanced colon cancer (NCT04069026)." (PMID 33916690, 2021). "Activation of β-catenin following IDO1 upregulation and subsequent AhR activation were analogous to data obtained with the colon cancer model." (PMID 34769098, 2021). "Our recent study demonstrated that kynurenine is co-induced with AHR in the same tumors, thus indicating that the kynurenine-AHR pathway is active in colon cancer cells." (PMID 31922097, 2020). "In intestinal cancer, the loss of the AhR enhances carcinogenesis in mouse models and treatment of wild-type mice with AhR agonists protects against chemical-induced and genetic models of colon cancer." (PMID 32932962, 2020). "Our lab has previously shown that AHR expression is elevated in colon tumors where it drives the expression of genes necessary for cell growth." (PMID 31922097, 2020). "Blocking the kynurenine/AhR interaction by CH-223191, an AhR antagonist, inhibited the proliferation of colon cancer cells." (PMID 32545442, 2020). "Recently, our laboratory discovered that the proto-oncogene MYC induces AHR expression in colon cancer." (PMID 31416966, 2019).
colon carcinoma (continued). "AHR is highly expressed in human colon cancer tissues, where it is localized in the nuclei of tumor cells." (PMID 31416966, 2019). "Administration of kynurenine, which is a tryptophan metabolite and an endogenous AhR agonist, activated β-catenin and proliferation of human colon cancer cell HCT116 and increased tumor growth in mice." (PMID 31675361, 2019). "Treating additional colon cancer cells with Kyn also promoted AHR nuclear translocation and induced the expression of the canonical of AHR target gene CYP1A1." (PMID 31416966, 2019). "Our results confirmed that SLC7A5, SLC1A5, TDO2, IDO1, and AHR were all elevated in colon cancer, while TPH1 was reduced." (PMID 31416966, 2019). "These inhibitors also reduced the levels of nuclear AHR in colon cancer cells, such as DLD1, as expected." (PMID 31416966, 2019). "Treating colon cancer cells (such as DLD1) that contain AHR in the nucleus with CH223191 antagonized nuclear translocation of AHR by Kyn." (PMID 31416966, 2019). "Studies of human colon cancer cells showed that AHR activation by TCDD drives colon cancer cell survival and migration and that overexpression of a constitutively active AHR causes stomach cancer." (PMID 30254109, 2018). "We also analysed the effect of sulindac sulfide on the aryl hydrocarbon receptor (AHR) pathway in vitro in colon cancer cells." (PMID 26183215, 2015). "The AhR mRNA expression profile of 967 human cancer cell lines showed that moderate levels of AhR are expressed in colon cancer cells." (PMID 26264025, 2015). "Over-expression of CYP1A1 and CYP1B1 in human colon tumors implies a pro-carcinogenic role for AhR target genes." (PMID 26264025, 2015). "Previous work in our lab revealed that AHR and its tryptophan-derived ligand, Kyn, play an important role in colonic cell growth, and thus AHR acts as a central integrator of growth signaling in colon cancer." (PMID 40353141, 2025). "In some cancers, such as colon cancer, AHR had dual roles in tumor oncogenesis and tumor suppression by promoting the integrity of the epithelial barrier, inhibiting inflammation, and antagonizing signals downstream of Wnt/β-catenin during the regenerative process." (PMID 40765830, 2025). "As TDO2-induced AhR activity was recently reported to upregulate PD-L1 in colon cancer, we hypothesized that TDO2/KYN may promote PD-L1 expression in this unique subset of TAMs." (PMID 38451784, 2024). "In addition, apigenin exhibited aryl hydrocarbon receptor (AhR) antagonist activity in Caco2 colon cancer cells." (PMID 39684479, 2024). "Altogether, these findings reveal the complexity of AhR as a tumor modulator in colon cancer." (PMID 38807762, 2024). "Other groups have corroborated a tumor suppressive function for AhR in colon cancer." (PMID 38807762, 2024). "ILA, as a ligand for AhR, has been confirmed to maintain the intestinal epithelial barrier and modulate immune function, with efficacy in mitigating intestinal ischemia–reperfusion injury, ulcerative colitis, and colon cancer." (PMID 39278929, 2024). "Furthermore, deletion of AhR in the colon cancer cells HCT116 and HT29 represses proliferation in a cell-specific manner." (PMID 37241719, 2023). "Our research has demonstrated that in an inflammation model of colon cancer where mice are treated with the carcinogen AOM and DSS (AOM/DSS), tumor development is enhanced with loss of the AhR and AhR ligands inhibit tumorigenesis in AhR+/+ mice." (PMID 38651159, 2023). "Finally, both AhR agonists TCDD and DIM suppress tumorigeneses in the colon in the murine model of colitis-associated colon cancer." (PMID 37241719, 2023). "In the CT26 colon carcinoma syngeneic mouse model, AhR blockade with a potent antagonist as monotherapy enhanced T cell function, decreased M2-like macrophages infiltration and drove antitumor immune response in vivo, resulting in the inhibition of tumor formation." (PMID 35173722, 2022).
colon carcinoma (continued). "Importantly, in the present study, we found that increased levels of AhR protein can be found not only in whole colon tumor tissue, but directly in EpCAM+ epithelial cells isolated from CRC tumors." (PMID 36077780, 2022). "Subsequently, AHR was identified as an inhibitor of the canonical Wnt signaling pathway in mouse intestine, being able to suppress intestinal carcinogenesis by degradation of β-catenin, with activated AHR expression also downregulating CTNNB1 expression in human colon cancer cell lines." (PMID 36499247, 2022). "While some of these effects could be linked with the anti-proliferative consequences of the AhR knockout, the present results also indicate that some FA metabolism genes, in particular SCD1, might be regulated by the AhR in colon cancer cells." (PMID 36077780, 2022). "However, the relationship of the AhR and the control of these important processes in colon cancer cells has been only partly explored." (PMID 36077780, 2022). "This indicates that inhibition of SCD1 expression in the absence of the AhR is not linked to reduced cell proliferation observed in AhR KO colon cancer cells." (PMID 36077780, 2022). "Together, these data indicate that aberrant expression of the AhR in colon cancer cells might also promote Akt pathway activity, with further implications for deregulation of cell growth, survival and metabolism, including FA metabolism." (PMID 36077780, 2022). "Together, our data indicate that disruption of AhR activity in colon tumor cells may, likely in a cell-specific manner, limit their proliferation, which could be linked with a suppressive effect on their endogenous FA metabolism." (PMID 36077780, 2022). "Using wild-type and the corresponding AhR knockout (AhR KO) variants of human colon cancer cell lines HCT116 and HT-29, we analyzed possible role(s) of the AhR in cell proliferation and metabolism, with a focus on regulation of the synthesis of fatty acids (FAs)." (PMID 36077780, 2022). "The primary goal of our study was thus to evaluate functional role(s) of the AhR in the control of proliferative and metabolic behavior of colon cancer cells, with a focus on FA metabolism genes, since the AhR seems to be upregulated in parallel with FA synthesis genes in colon tumors." (PMID 36077780, 2022). "Several studies have indicated that the AhR is overexpressed in colon tumor tissue." (PMID 36077780, 2022). "Yet, it is unknown whether microbial indole production is protective or deleterious in the context of increased IDO1 or AhR expression in colon cancer." (PMID 33916690, 2021). "Interestingly, blocking the binding of kynurenine to AHR also reduces the proliferation of colon cancer cells, however, less dramatically than inhibiting kynurenine production." (PMID 31922097, 2020). "Moreover, studies of human colon cancer cells show that AHR activation by the dioxin TCDD drives colon cancer cell survival and migration." (PMID 31416966, 2019). "Indeed, inhibiting Kyn synthesis had more dramatic effects on viability of colon cancer cells than inhibiting the binding of AHR to Kyn." (PMID 31416966, 2019). "We found that only Kyn was capable of inducing nuclear translocation of AHR in colon cancer cells." (PMID 31416966, 2019). "Interestingly, only Kyn (the most abundant Trp metabolite present in tumors) and no other Trp metabolites was capable of inducing translocation of AHR into the nucleus of colon cancer cells." (PMID 31416966, 2019). "AHR expression was also elevated in colon cancer samples by our laboratory." (PMID 31416966, 2019). "Thus, our results indicate that Kyn is necessary to sustain the proliferative state of colon cancer cells at least in part by promoting AHR nuclear translocation and transcriptional activation." (PMID 31416966, 2019). "In addition, studies using human colon cancer cell lines showed that AhR activation in vitro increases cell proliferation, migration, and invasion via transactivation of the EGFR/ERK signaling pathway." (PMID 26264025, 2015).
colon carcinoma (continued). "In addition, it was shown that AhR activation in colon cancer cells induces expression of multiple target genes including matrix metalloproteinase (MMP)-9, calcium ion flux, pro-inflammatory IL-1β and the drug transporter BCRP/ABCG2." (PMID 26264025, 2015). "Activated AHR also downregulated CTNNB1 expression in multiple human colon cancer cell lines." (PMID 25286307, 2014). "One study showed that AHR expression was raised in tumor tissues from a variety of sources, including the breast, colon, and lung, whereas another study found that AHR deletion led to increased proliferation of colon cells and exacerbated growth in a colon cancer tumor model." (PMID 39201782, 2024). "Thus, the Kyn-AhR signaling pathway contributes to colon cancer progression." (PMID 38518996, 2024). "Therefore, we tested whether indolimines are AHR ligands and found that all three indolimines are AHR agonists in human colonic tumor cells, capable of activating the AHR at nanomolar levels." (PMID 37755265, 2023). "In addition, two FA elongases, ELOVL5 and 6, were also downregulated in AhR KO colon cancer cells." (PMID 36077780, 2022). "Since the Wnt/β-catenin pathway is considered to be a major regulator of the proliferation of colon cancer cells, and the AhR has been proposed to interfere with β-catenin-dependent signaling in colon cells, we also analyzed the levels of β-catenin in wild-type and AhR KO HCT116 cells." (PMID 36077780, 2022). "Thus, the Kyn-AhR signaling pathway is one of the major contributors to colon cancer." (PMID 33916690, 2021). "Chromatin immunoprecipitations for CREB, AhR or β-catenin from extracts from fascin-positive or -negative human colon carcinoma cells identified that CREB and AhR specifically associate with the −219/+114 region of the FSCN1 promoter in fascin-positive colon carcinoma cells." (PMID 19340314, 2009). "In the colon cancer spheroids, the TDO2-mediated activation of AhR was found to promote a launch of the Wnt/β-catenin signaling pathway." (PMID 37232717, 2023). "Aqueous coffee extracts induced the Ah- responsive CYP1A1, CYP1B1, and UGT1A1 genes in Caco-2 colon cancer cells and YAMC mouse colonocytes, and these responses were abrogated in their corresponding AhR knockout (AhR-KO) cell lines." (PMID 36769029, 2023). "The observation that the AhR and TCDD treatment decrease colonic stem and progenitor cells correlated with the AhR-dependent decrease of colonic tumor formation." (PMID 38651159, 2023). "AhR expression activated by AhR agonists I3C, IAA, or 3MC lowers the expression of CTNNB1 in human colon cancer cell lines." (PMID 37232717, 2023). "The discovery that the AhR represses FOXM1 expression in the colon is consistent with a previous report showing that FOXM1 signaling contributes to formation and growth of colonic tumors." (PMID 38651159, 2023). "Collectively, these observations have led us to explore the functional role of the AhR, using full CRISPR/Cas9-mediated knockout of the AhR in two models of colon carcinoma cells, HCT116 and HT-29 cell lines." (PMID 36077780, 2022). "In models of colon cancer, I3C and DIM are chemopreventive in an AHR-dependent fashion which also is responsive to microbial production of indole AHR ligands from dietary tryptophan metabolism." (PMID 34660663, 2021). "Absence of intestinal AHR activity results in dysbiosis of the gut microbiome and a compromised epithelial barrier with increased intestinal inflammation, enhanced “leakage” with susceptibility to pathogenic bacteria (e.g., Citrobacter rodentium) and colon cancer." (PMID 34660663, 2021). "The interaction between AhR and Kyn can be inhibited with CH223191 in order to reduce the proliferation of colon cancer cells and increase preferential death of colon cancer cells." (PMID 32957545, 2020). "Therefore, we asked whether Kyn regulates AHR activity in colon cancer cells." (PMID 31416966, 2019).
colon carcinoma (continued). "In Caco2 colon cancer cells, GEN (50 μM) decreased nuclear AHR levels and prevented TCDD-induced AHR nuclear localization." (PMID 31652854, 2019). "We performed IHC for TDO2, TPH1, AHR, serotonin, and TPH2 in paraffin-embedded patient-derived normal and colon cancer tissues to confirm our TCGA results." (PMID 31416966, 2019). "To validate these results, we performed RT-qPCR for SLC1A5, SLC7A5, TPH1, TDO2, IDO1, AHR, and MYC in colon cancer and normal tissue of the same patients." (PMID 31416966, 2019). "Blocking the interaction between AHR and kynurenine with CH223191 reduced the proliferation of colon cancer cells." (PMID 31416966, 2019). "We demonstrated that in human colon cancer cell lines, upon AhR activation by TCDD, Src-mediated cross-talk between AhR and EGFR results in ERK1/2 activation and enhanced cell proliferation." (PMID 26264025, 2015). "To explore how AhR activation affects α-defensin 1 expression in a more controlled environment, we employed additional in vitro experiments with murine adenocarcinoma cells, MC38, and human colon carcinoma, Caco2 cells." (PMID 39894796, 2025). "AhR-dependent repression of FOXM1 was observed in crypts adjacent to colon tumors and tumors, stem and progenitor cells and chromatin immunoprecipitation showed that TCDD induced formation of the AhR:ARNT complex in regions of the FOXM1 promoter containing a cis-acting AhRE binding site." (PMID 38651159, 2023). "When these data are compared with findings from another study on human colon cancer cell lines DLD-1, SW480, and HCT116, there is a controversy regarding whether AhR agonists enhance or weaken β-catenin and its signal." (PMID 37232717, 2023). "In colon cancer, most but not all studies suggest that the AhR exhibits tumor suppressor activity which is enhanced by AhR ligands acting as agonists." (PMID 38651159, 2023). "Notably, BAY-218, a selective AhR blocker, increased therapeutic activity of anti-PD-L1 antibody in the CT26 colon carcinoma model." (PMID 35173722, 2022). "Nevertheless, other studies did not observe the AhR agonist-mediated degradation of β-catenin in human colon cancer cell models." (PMID 36077780, 2022). "Collectively, these findings suggest that TNF-α induced DNA damage involves JNK signaling pathway rather than AhR and NF-κB pathways in colon cancer epithelial cells." (PMID 33961948, 2021). "Furthermore, protein level AhR expression different in human stomach cancer epithelial cell line (AGS, MKN45, N-87, SCM-1), human colon cancer epithelial cell line (HCT116) and normal cells (AMJ2, MMC, SVECs, HUVECs)." (PMID 25226618, 2014). "IL11 has not been previously associated with AHR but is known to suppress CD4+T cells mediated anti-tumor immunity, and the IL11/STAT3 inhibition increased MHC-I expression and T cell infiltration in colon cancers." (PMID 40283908, 2025). "This disconnect suggests that colon cancer cell lines may not always be reliable for predicting the in vivo role of AhR in colon carcinogenesis." (PMID 26264025, 2015). "Therefore, potential impact of AhR on colon cancer cell behavior is not fully clear." (PMID 36077780, 2022). "This, together with our observation that the levels of total/active β-catenin and activity of the TCF/LEF reporter were not affected by the AhR loss in HCT116 cells, indicates that the potential role of the AhR in control of proliferation of colon cancer cells may not depend on β-catenin activity." (PMID 36077780, 2022). "A recent study using the colon carcinoma cell line Caco-2 reported that β-catenin was not reduced after TCDD exposure, and AhR agonistic activity of IAA was only apparent at a higher dose (0.5–1 mM)." (PMID 31675361, 2019).